TAGLN2 (transgelin 2)
Diseases named in the same sentence as TAGLN2 in open-access papers (continued):
Sharing a sentence is not in itself a finding about the gene and the disease.
cancer (continued). "Because the expression of transgelin-2 is significantly upregulated in macrophages, we speculate that transgelin-2 function may be more important for professional APC-based cancer immunotherapy." (PMID 33898417, 2021). "Thus, transgelin-2 plays a dominant role in the regulation of cell proliferation in PDAC, which may be different in other types of cancer." (PMID 30041673, 2018). "However, thorough research on TAGLN2 is lacking in pan-cancer." (PMID 37476180, 2023). "TAGLN and TAGLN3 are homologues of TAGLN2, and TAGLN3 is a novel neuron-specific protein and has not been reported in cancer." (PMID 21304530, 2011).
bacterial infection (3 papers, 2017 to 2023). "Although transgelin-2 is constitutively expressed in lymphocytes, its expression is significantly upregulated under inflammatory conditions such as bacterial infection." (PMID 33898417, 2021). "Surprisingly, macrophages treated with IFN-γ and LPS highly expressed TAGLN2 but no other TAGLN family members, suggesting a unique function of TAGLN2 after bacterial infection." (PMID 28821818, 2017). "Here, we demonstrated that TAGLN2 mediated large-scale actin dynamics during the engulfment of bacteria, thereby augmenting phagocytosis, and that the regulation of phagocytosis by TAGLN2 played a pivotal role in host defense against bacterial infection." (PMID 28821818, 2017). "Thus, the development of cell-permeable peptides with transgelin-2 functions have potential clinical value to treat sepsis induced by bacterial infection." (PMID 33898417, 2021). "Furthermore, Tagln2–/– mice show higher mortality after bacterial infection than their wild-type littermates, revealing that transgelin-2 is essentially required for host defense." (PMID 33898417, 2021). "Finally, we determined whether regulation of phagocytosis by TAGLN2 affects the host response to bacterial infection." (PMID 28821818, 2017). "DRAM1 was also in close proximity to FAM49B (related to bacterial infection), THBS1 (related to autophagy), TAGLN2 (related to phagocytosis), and PDIA3 (related to autophagy), which displayed higher expression levels in and around the cell nucleus." (PMID 37919720, 2023).
immune diseases (2 papers, 2016 to 2017). "High expression of transgelin-2 in T-cells and B-cells suggests that this small actin-stabilizing protein is involved in immune diseases." (PMID 27232882, 2016). "High expression of TAGLN2 in B-1 cells suggests that TAGLN2 may be involved in immune diseases." (PMID 28910360, 2017).
infection (2 papers, 2017 to 2024). The state of being infected such as from the introduction of a foreign agent such as serum, vaccine, antigenic substance or organism. "Therefore, chronic exposure to infection or external radiation led to persistent TAGLN2 expression, which induced cytoplasmic ssDNA aggregation and triggered continuous low levels of IFN-activated resistance signature ISG upregulation in GC patients." (PMID 39168971, 2024). "In addition to pathogen infection, we also found that the mRNA expression of TAGLN2 was upregulated by irradiation treatment at both 4 Gy or 6 Gy." (PMID 39168971, 2024). "Therefore, consistent exposure to a low level of infection or external radiation can induce lasting expression of TAGLN2." (PMID 39168971, 2024).
TAGLN2 also shares sentences with these, for which no sentence is quoted: esophageal squamous cell carcinoma (3 papers); glioblastoma (3); cognitive deficits (2); preeclampsia (2); renal cell carcinoma (2); acute coronary syndrome (1); astrocytomas (1); atherosclerosis (1); Barrett adenocarcinoma (1); biliary tract cancer (1); carcinoma in the stomach (1); cervical cancer (1); endothelial dysfunction (1); Epstein-Barr virus infection (1); familial hypercholesterolemia (1); hepatitis B (1); Hernia (1); HIV-1 infection (1); Hyperinsulinemia (1); hyperlipidemia (1); infectious disease (1); kidney cancer (1); lipid metabolism disorders (1); lipoma (1); lupus erythematosus (1); metabolic disease (1); metastatic melanoma (1); mucinous tumor (1); neurodevelopmental disorder (1); Obesity (1).
A further 7 diseases each share a sentence with TAGLN2 in 1 paper.